APOE (apolipoprotein E)
Diseases named in the same sentence as APOE in open-access papers (continued):
Sharing a sentence is not in itself a finding about the gene and the disease.
infection (197 papers, 2008 to 2026). The state of being infected such as from the introduction of a foreign agent such as serum, vaccine, antigenic substance or organism. "Inheriting the APOE ε4 allele increases the severity of AD pathology because this gene predisposes individuals to infections by compromising the hosts immune system,18, –20 and disturbances in the lipid metabolism." (PMID 40171450, 2025). "The critical role of ApoE in affecting susceptibility to infection was demonstrated using APOE−/− mice in a model of Mycobacterium smegmatis, Klebsiella pneumoniae, and Cryptosporidium parvum infection." (PMID 41416135, 2025). "The APOE-ε4 allele has a nuanced relationship with susceptibility to infections, offering protection against some viruses while increasing the risk for others." (PMID 39858858, 2025). "In this study, we determined the APOE genotype from archival paraffin tissue blocks of 38 patients with fatal COVID‐19 who died either from infection with ancient SARS‐CoV‐2 or with the Omicron variant." (PMID 41253293, 2025). "In this study, we evaluated the effect of TcdA on fluid accumulation and inflammation in the ileal loop mouse model and the effect of infection by C. difficile on animal survival, weight loss, and diarrhea in APOE knockout (APOE −/−) and wild-type mice." (PMID 41416135, 2025). "Variants of ApoE isoforms have been shown to differentially impact SARS‐CoV‐2 cellular infection and COVID‐19 outcome in SARS‐CoV‐2 patients and human iPSC‐based models as well as a mouse model." (PMID 37822714, 2023). "SARS-CoV-2 also displays APOE-isoform-dependent neurotropism, where neurons and astrocytes bearing the APOE4 mutation as well as co-cultures of neurons with astrocytes are more susceptible to infection in hiPSC brain organoids." (PMID 37146581, 2023). "An ApoE neutralizing antibody can efficiently inhibit the infection of SARS‐CoV‐2 and its variants of concern." (PMID 37822714, 2023). "Taken together, our findings demonstrated a correlation between the high expression of APOE caused by the infection of Mlep and the inhibition of pro-inflammatory and antimicrobial innate immune responses in macrophages." (PMID 35013182, 2022). "Stress, inflammation, and other events can lead to reactivation of the virus, causing a productive infection and consequent damage which, it is suggested, is likely to be greater in people who carry the type 4 allele of the apolipoprotein E gene (APOE-ε4)." (PMID 34205498, 2021). "Hepatitis C virus (HCV) infection is influenced by genetic (e.g., APOE polymorphisms) and environmental factors between the virus and the host." (PMID 34684338, 2021). "SPP1 or APOE knockdown in Jurkat T cells increased susceptibility to HIVGKO infection, suggesting that they have antiviral properties." (PMID 33504604, 2021). "Infection with P. gingivalis exacerbated atherogenesis in apolipoprotein E (ApoE)-deficient mice, and the proximal aortic lesion size in P. gingivalis-inoculated mice was 2-fold larger than that in control mice." (PMID 33202751, 2020). "HCV particles produced early in infection are associated with a higher amount of apoE, while later in infection the HCV associated apoE concentration decreases." (PMID 33151933, 2020). "Consistent with this, the human APOE ε4 allele modifies host responses to infection, such as the human immunodeficiency virus." (PMID 30412599, 2018). "For example, infection is linked to ApoE-ε4 expression, atherosclerosis, diabetes type 2, and neurotrauma (as this would affect the blood–brain barrier)." (PMID 30250480, 2018). "A recent study shows that the infection burden (IB) consisting of common pathogens is associated with AD after adjusted for ApoE genotype and various comorbidities." (PMID 27054030, 2016). "Both have similar age-dependence, vascular pathology, genetic underpinnings including the central role of APOE, Aβ involvement, and association with infection." (PMID 24656052, 2014).
infection (continued). "APOE polymorphisms affect not only the function of protein in cholesterol transport but also other processes including infection and immunity (below) and tissue repair." (PMID 24656052, 2014). "In this study, we found that APOE-deficient mice had significantly less C. parvum oocyst shedding measured by quantitative PCR in stools on the first and third days post-infection, when the infection peaks." (PMID 24586873, 2014). "By contrast, infection of ApoE-deficient mice with S. mansoni cercariae resulted in reduced HDL-C, although levels do not change during chronic exposure to schistosome eggs." (PMID 25051269, 2014). "We found increased ileal expression of CAT-1 mRNA transcripts in the ileum from undernourished plus infected APOE 4/4 TR mice in comparison to wild-type and APOE-deficient mice on day 7 post-infection." (PMID 24586873, 2014). "ApoE-deficient mice have been shown to have impaired innate immune defenses in models of Listeria monocytogenes and Klebsiella pneumonia infections." (PMID 24586873, 2014). "Our first aim was to confirm that L. major causes a self-limited infection in apoE KO mice similar to that observed in the wild-type control C57BL/6 mice." (PMID 23710353, 2013). "Our results reveal that the association of ApoE with HSV1 particles promotes infection by facilitating both virus attachment to and release from the cell surface, and that this is the result of a modified interaction between ApoE-carrying virus particles and heparan sulfate on the cell surface." (PMID 40295730, 2025). "Furthermore, it has been experimentally shown that oral infection of Apolipoprotein E (ApoE)-deficient mice with H. cinaedi results in the more frequent development of atherosclerotic plaques in the lumen of vessels compared to uninfected ApoE-deficient mice." (PMID 38650874, 2024). "For the pursuance of new strategies that can address cognitive loss in MS, APOE and infection with SARS-CoV-2 may be significant risk factors for MS." (PMID 37508898, 2023). "In this study, we demonstrated that an ApoE neutralizing antibody could block the infection of SARS‐CoV‐2 and its Delta and Omicron variants effectively." (PMID 37822714, 2023). "Moreover, the combination of transcriptional analysis, qPCR, and killing assay showed that ApoE deficiency led to enhanced cholesterol biosynthesis in macrophage, ameliorating anti-infection ability." (PMID 37529351, 2023). "Similarly, APOE ε4 carrier status in a large rural Ghanaian population was associated with a protective effect against infection and improved fertility among women exposed to high pathogen levels." (PMID 37496074, 2023). "The result of leading-edge analysis showed that ApoE was associated with the largest number of enriched gene sets, and we found that expression of ApoE increased by day 14 post-infection, despite expression levels of ApoE comparable to control by day 3 post-infection." (PMID 37529351, 2023). "Moreover, the APOE-ε4 allele, a well-established risk factor for AD, modulates the host’s susceptibility to infection by numerous pathogens, including HSV-1, which is in line with the suspicion of viral involvement in the etiology of AD." (PMID 37496074, 2023). "Moreover, the ApoE neutralizing antibody is very effective in inhibiting the infection of not only the parental SARS‐CoV‐2 but also its variants including the Delta strain and the Omicron strain." (PMID 37822714, 2023). "Thus, ApoE neutralizing antibodies can provide broad protection from infection by continuously emerging SARS‐CoV‐2 variants of concern, overcoming the limitation of antibodies targeting the spike protein for which the encoding gene can be frequently mutated." (PMID 37822714, 2023). "Moreover, an ApoE neutralizing antibody can block the infection by SARS‐CoV‐2 and its variants of concern." (PMID 37822714, 2023).
infection (continued). "As alleles ɛ2, ɛ3 and ɛ4 in APOE gene correspond to genotypes rs7412-T/rs429358-T; rs7412-C/rs429358-T; and rs7412-C/rs429358-C, respectively, we evaluated the combination of the two SNPs rs7412 and rs429358 in the risk of infection." (PMID 35508522, 2022). "It has been hypothesized that elevated cholesterol and oxidized lipoprotein levels, linked to the effects of ApoE ε4/ε4 variant, is associated with increased pneumocyte susceptibility to infection and to exaggerated lung inflammation." (PMID 35793369, 2022). "Although APOE has recently been associated with increased susceptibility to infections of several viruses, whether and how APOE and its isoforms affect SARS-CoV-2 infection remains unclear." (PMID 35915083, 2022). "In HCV, ApoE polymorphism was reported to predict various infection outcomes." (PMID 33924242, 2021). "However, there appears to be emerging evidence that homozygosity for the ApoE e4 genotype increases the risk of infection and of severe COVID-19 disease from the UK Biobank." (PMID 33192744, 2020). "These questions are approached by examining basic mechanisms of apoE cell biology relevant to energy metabolism with insights into how adaptive responses to infections could facilitate reproduction, but increase the risk of aging-associated diseases." (PMID 32587511, 2020). "• ApoE determines severity of damage (or susceptibility to infection) by diverse pathogens." (PMID 30250480, 2018). "Susceptibility to infection by the intracellular bacterial pathogen, Chlamydia pneumoniae, may also be enhanced by the APOE ε4 allele by a mechanism involving increased attachment to host cells." (PMID 30412599, 2018). "Moreover, the hazard ratio for the infection was 13.02, indicating that the ApoE−/− mice were 13 times less susceptible to ECM than the WT mice." (PMID 27647324, 2016). "Consistent with this hypothesis, development of atherosclerotic lesions was increased significantly by infection of apoE−/− mice with lentivirus (LV) encoding mouse VNN1 (LV-VNN1)." (PMID 27281478, 2016). "Although exhibiting more parasite elimination, undernourished APOE-deficient mice had greater inflammatory cytokine responses and mucosal atrophy in the ileal tissue one week-post inoculum, accompanied by greater weight deficits following 7 days of infection." (PMID 24586873, 2014). "This specific infection/undernutrition/APOE genotype mouse model has permitted us to examine whether pro-inflammatory states associated with APOE transgenic mice would be beneficial against cryptosporidial infections." (PMID 24586873, 2014). "Chow-fed apoE-deficient mice were exposed to 1) chronic intranasal infection with C. pneumoniae (Cpn group), 2) recurrent intravenous infection with A. actinomycetemcomitans (Aa group), 3) a combination of both types of infection (Cpn + Aa group), or 4) infection with the vehicle (control group)." (PMID 24131481, 2013). "However there was some evidence to suggest that apoE genotype influenced the course of infection, with homozygosity for the ε4 allele associated with an accelerated course of disease." (PMID 20109174, 2010). "The potential relationship between infection by oral P. gingivalis and regulation of AD risk associated genes in a genetically modified mouse model (ApoE−/−) could uncover new insights into the mechanisms through which infection with this oral bacterium may contribute to AD pathophysiology." (PMID 40171450, 2025). "Neuropsychological test performance may also be influenced by sociodemographic (e.g. age, sex), clinical (e.g. comorbidities, hospitalization in the acute phase of infection, depressive symptoms) and predisposing factors (e.g. apolipoprotein ɛ4 (ApoE-ɛ4) genotype)." (PMID 39016843, 2025). "Thus, although apoE may exert independent effects on the risk of infection and disease severity, these comorbidities should be considered." (PMID 36089575, 2022).
infection (continued). "As apoE isoforms vary in strength of binding to liver cell receptors (apoE4 > E3 > E2) individuals with the APOE Ɛ4 allele could have less sporozoite infection in the liver and a lower multiplicity of infection (MOI), a measure of Plasmodium spp." (PMID 24116184, 2013). "More significantly, extracellular apoE3 lipoproteins significantly promoted HBV infection in a dose-dependent manner when mixed with apoE-null HBV prior to infection." (PMID 42267825, 2026). "In our study, we determined the APOE genotype from archival paraffin blocks of patients who died of COVID‐19 in the first wave of infections in spring 2020 and of those who died in 2022 during Omicron (lineage B.1.1.529) abundance." (PMID 41253293, 2025). "Next, we investigated the HSV1 growth kinetics of multiple (MOI 0.1) or single infection (MOI 10) cycles on GMK in the presence of 5 μM ApoE isoforms." (PMID 40295730, 2025). "Human apolipoprotein E (ApoE) has been shown to play important roles during primary infection and pathogenesis of several viruses." (PMID 40295730, 2025). "TaqManTM Mouse AD arrays were performed on orally infected ApoE−/− mice with confirmed P. gingivalis entry and compared with sham infected mice brains (N = 4) at 12- and 24-weeks post infection." (PMID 40171450, 2025). "Western blot analysis of plasma samples collected 5 days post-infection confirmed the expression of human APOE in mice infected with AdAPOE4 and AdAPOE4mut1." (PMID 41354325, 2025). "In endothelial tissue, particularly during severe infection, APOE exhibits antibacterial activity, while T3SS affects actin cytoskeleton dynamics." (PMID 41164165, 2025). "For example, carriers of APOE-ε4 are more prone to infections like HSV-1 and EBV, often experiencing higher rates of infection or more severe disease outcomes." (PMID 39858858, 2025). "The findings that ApoE 4 facilitates attachment or release of HSV1 from the cell surface indicate that ApoE primarily facilitates infection in the context of cell-free spreading." (PMID 40295730, 2025). "In contrast, APOE-ε4 appears to provide a protective advantage against HCV and Hepatitis B Virus (HBV), lowering infection risk or enhancing immune regulation." (PMID 39858858, 2025). "Despite the suggested involvements of ApoE in the infection process of HSV1, little is known about how both interact mechanistically on a molecular level." (PMID 40295730, 2025). "ApoE mRNA levels were significantly increased in infected macrophages as compared to uninfected controls between 8 and 24 hours post-infection." (PMID 40439406, 2025). "Such an influence becomes more important in the multiple infection cycle experiment, where ApoE-coated progeny virions are involved in subsequent cellular infection cycles." (PMID 40295730, 2025). "We found that MHV68 infection of primary macrophages stimulated ApoE expression in a type I interferon (IFN)-dependent manner." (PMID 40439406, 2025). "At 24 hours post-infection, when an increase in ApoE mRNA levels was first observed, mRNA levels of ORF6 and ORF59, but not ORF50 and ORF9, were decreased in ApoE-/- macrophages." (PMID 40439406, 2025). "Remarkably, there exists epidemiological evidence pointing to an intriguing interplay between infectious burden and APOE ε4 carrier status, hinting at a potential safeguarding influence of APOE ε4 against infection and its enduring cognitive consequences." (PMID 39880097, 2025). "As expected, MHV68-infected macrophages demonstrated an increase in ApoE protein levels following MHV68 infection." (PMID 40439406, 2025). "Environmental, APOE, aging, and vascular disease, TBI and risk factors associated with diet, the immune system, mitochondrial function, metal exposure, and infection." (PMID 39640295, 2024). "It is believed that APOE-ε4 is one of the important molecules that regulate the immune system and that it can control the infection outcome from several pathogens." (PMID 39224577, 2024).
infection (continued). "For instance, apoE is an essential composition of mature HCV particle engaging in the infection process and able to protect the virus from immune clearance." (PMID 38976030, 2024). "Infection severity is inversely proportional to the VLDL elimination due to reduced apolipoprotein E and lipoprotein lipase." (PMID 38449886, 2024). "Specifically, we found that the expression of APOE was significantly upregulated in the acute death cases compared to both normal and long infection cases during SARS-CoV-2 infection." (PMID 38752789, 2024). "The ApoE−/−+agomir-miR-19a/b-treated mice developed lung parenchyma lesions after 5 days of infection, whereas ApoE−/−+agomir-NC-treated mice showed an expansion of lesion area that persisted until 7 days post-infection." (PMID 38435118, 2024). "The ApoE neutralizing antibody blocked the infection of the ALI organoid cultures by the SARS‐CoV‐2 Omicron variant efficiently." (PMID 37822714, 2023). "In contrast to our findings, abdominal sepsis in ApoE-/- mice aged 22-24 weeks which had been fed an atherogenic diet for 16 weeks prior to infection resulted in an acceleration of atherosclerotic plaque formation over a 5 month period." (PMID 37033482, 2023). "The ApoE neutralizing antibody blocked the infection of hACE2‐HEK, Calu‐3, and astrocytes by Omicron virus substantially, similar to the infection by the parental SARS‐CoV‐2 and the Delta strain." (PMID 37822714, 2023). "The infection hypothesis of AD proposes that chronic infection with viral, bacterial, and/or fungal pathogens might be a trigger for AD onset during aging—probably via inflammatory processes—the risk of which seems predominantly high in apolipoprotein E (APOE) ε44 allele carriers." (PMID 36984505, 2023). "Children who are APOE-ε4 carriers living in low-income settlements in Brazil with high infection rates grow faster than non–APOE-ε4 carrier children." (PMID 37556539, 2023). "We then tested if the ApoE neutralizing antibody can block infection by the SARS‐CoV‐2 Omicron strain." (PMID 37822714, 2023). "Survival assessments in smaller cohorts (n=3) of Western diet-fed ApoE-/- mice infected with 5 x104 cfu and 104 cfu also demonstrated high mortality rates within 72 hours of infection (3 and 2 were culled respectively)." (PMID 37033482, 2023). "Anti-Zika E protein antibodies neutralized the infection much more efficiently, but the partial neutralization observed with anti-ApoE antibodies further confirms the presence of ApoE at the surface of the viral particles." (PMID 35902969, 2022). "Previous studies have discussed the role of APOE genotypes in infection, especially in respiratory disease." (PMID 36005151, 2022). "Further cryo-TEM analysis was performed according to the Tokuyasu method with samples prepared in the same conditions of infection, for immunogold labeling of the Zika E and ApoE proteins." (PMID 35902969, 2022). "The neutralization abilities of both anti-ApoE and anti-Zika Abs were compared to their corresponding isotype, represented as the 100% of infection." (PMID 35902969, 2022). "Huh7.5 cells were infected at an MOI of 1 and the colocalization of the ApoE and Zika E proteins was studied by confocal microscopy 6-, 12-, 24- and 48-h post-infection." (PMID 35902969, 2022). "Lysates were obtained from the infected cells and subjected to co-immunoprecipitation assays with anti-ApoE Abs at 48 h post-infection, with detection of the co-immunoprecipitated proteins by Western blotting." (PMID 35902969, 2022). "This distribution was confirmed by the strong colocalization of ApoE, Zika E protein and calnexin, a marker of the ER compartment, 24 h post-infection." (PMID 35902969, 2022).